HIF1A (hypoxia inducible factor 1 subunit alpha)
Diseases named in the same sentence as HIF1A in open-access papers (continued):
Sharing a sentence is not in itself a finding about the gene and the disease.
melanoma (continued). "Studies using melanoma cell lines revealed that the suppression of ASS1 expression is due to Hif1α binding to the promoter region of ASS1, but this suppression can be relieved under ADT by induced downregulation of Hif1α and binding of upregulated c-Myc to replace Hif1α." (PMID 34299249, 2021). "However, in a recent study, we did not observe differences in HIF-1α protein levels among melanoma tissues." (PMID 33007949, 2020). "Thus, we can propose that inhibition or activation of the protein kinases such as AKT, HIPK2, AMPK, MET, JNK, HIF-1α, and CD44 by treatment with CDPs in the mouse melanoma model could involve the blocking of the substrate binding site as a molecular mechanism." (PMID 32793477, 2020). "Since ACF decreased glucose availability and affected the HIF-1α pathway under normoxic conditions, we hypothesized that the induction of an ER stress response pathway could be responsible for the ACF-dependent suppression of MITF in melanoma cells." (PMID 33396270, 2020). "Since ACF, by inhibiting HIF-1α-regulated pathways in normoxia, can reduce glucose availability and induce ER stress while suppressing ATF4 protective pathways, this drug could represent an efficient treatment against melanoma." (PMID 33396270, 2020). "Altogether, these results indicate that ACF differentially modulates HIF-1α-dependent pathways in melanoma, and suggests that under normoxic conditions VEGF expression could be regulated by HIF-1α-independent mechanisms." (PMID 33396270, 2020). "Many melanomas display the activity of HIF-1α also under non-hypoxic conditions." (PMID 31461993, 2019). "Actinomycin D suppressed the upregulation of TRPM1 mRNA, which is transcriptionally activated upon treatment of melanoma cells with BRAF inhibitor 37 but did not affect HIF1A mRNA, confirming that the dose of actinomycin used was sufficient to block transcription completely." (PMID 31727958, 2019). "Our discoveries that manipulations of CXCR7 have minimal impact on HIF-1α mRNA level and VHL expression, whereas significantly modulate HIF-1α accumulation in the presence of the proteasome inhibitor MG132, suggest that CXCR7 promotes HIF-1α translation in melanoma cells." (PMID 30804329, 2019). "Furthermore, to investigate whether CXCR7-induced HIF-1α accumulation was attributed to translational regulation, the proteasome inhibitor MG132 was administered to melanoma cells under normoxic conditions." (PMID 30804329, 2019). "Decreased HIF1α activity by RNA interference significantly inhibited E-cadherin expression and increased Vimentin expression, and reversed the process of EMT, suggesting that HIF1α may be a new target to treat melanoma metastasis." (PMID 31371307, 2019). "Melanoma cells could still partially compensate for reduced cellular bioenergetics by glutamine utilization under dual inhibition of OXPHOS and glycolysis, while triple inhibition of PGC-1α, HIF-1α, and glutamine utilization completely blocked cell growth." (PMID 30771209, 2019). "Furthermore, we transfected the BrafV600E; Phd2−/− melanoma cells with a non-degradable HIF-1α that also resulted in elevated pAkt and pS6K levels." (PMID 30575721, 2018). "In addition, MG132, a 26S proteasome inhibitor, did not rescue vanillin-mediated HIF-1α reduction in melanoma cells, suggesting that vanillin reduces HIF-1α using a mechanism that is independent of proteasomal degradation." (PMID 28257048, 2017). "To assess whether HMGB1 release under hypoxic culture condition was dependent on HIF1α or not, we knocked HIF1α down using siRNA in two human melanoma cell lines." (PMID 27426915, 2016). "However, the relationship between HIF1α and IGFBP5 in human melanoma cells remains to be verified." (PMID 26010068, 2015). "Many tumor types including melanoma stabilize HIF-1α under non-hypoxic conditions." (PMID 26547841, 2015).
melanoma (continued). "Unlike the case of melanoma where an increase in HIF1α expression under normoxia is due to increased HIF1α protein stability, we have shown that in PC cells the increase in HIF1α may be due to increased HIF1α protein translation." (PMID 23342109, 2013). "HO-1 was upregulated in 3/3 melanoma cell lines (WM1158, WM983-B, and WM852); TACO-1 was downregulated in WM1158 melanoma cells and not detectable in two melanoma cell lines (Lu1205 and WM983-B) (data not shown); and HIF-1α was upregulated in 3/3 melanoma cell lines (WM1158, WM983-B, TPF10-741)." (PMID 22912665, 2012). "Moreover, we were able to demonstrate that CTGF expression in malignant melanoma is regulated by hypoxia-inducible factor HIF-1α, whereas members of TGFβ superfamily have no impact on modulation of CTGF expression levels." (PMID 21673687, 2011). "Our results suggest that development of new therapeutic agents that inhibit HIF-1α function may be of use in the treatment of human melanoma regardless of the hypoxic condition of the tumor." (PMID 19919690, 2009). "However the biological significance of upregulated HIF-1α under normoxic conditions for initiation and progression of melanoma has not been elucidated." (PMID 19919690, 2009). "Analysis of BRAF and NRAS mutations in our human melanoma cell lines shows that WM3211 cells do not have the common activating mutations in these genes, yet these cells express increased amounts of HIF-1α protein and mRNA under normoxic conditions." (PMID 19919690, 2009). "Therefore, HIF-1a seems to regulate the expression of the TET2 enzyme, contributing to the modified epigenetic landscape of melanoma and it might represent a future target for melanoma therapies." (PMID 40427015, 2025). "Therefore, targeting HIF-1α function, regardless of the hypoxic condition of the tumor, may be a useful strategy to treat human melanoma." (PMID 33396270, 2020). "Moreover, it was shown that the Elongator complex promotes glycolysis in melanoma cells through direct, codon-dependent, regulation of the translation of Hypoxia Induced factor 1 α (HIF1A) mRNA, and the maintenance of high levels of HIF1α protein providing strong resistance to anti-BRAF therapy." (PMID 30597914, 2018). "Thus, the lactate increase observed in SOX2-silenced acidic and non-acidic melanoma cells could be able to contribute to HIF1α expression and glycolytic re-conversion." (PMID 30466459, 2018). "Regardless of the mechanism for the ability of AA and A2P to decrease HIF-1α levels and inhibit HIF transcriptional activity, the important question is whether blocking the HIF pathway decreases some of the malignant properties of the WM9 metastatic melanoma cells." (PMID 26547841, 2015). "Moreover, in a subset of breast, prostate, melanoma and renal carcinoma cell lines, HIF-1α accumulation during hypoxia was independent of DNA hypermethylation of the PHD3 promoter region, which suggests its role in other pathways and hydroxylase independent function." (PMID 24195777, 2013). "While previous studies highlighted roles for HIF-1α and VEGF in melanoma angiogenesis, there are no previous data on the relative importance of angiogenesis or response to anti-angiogenic therapy in BRAFWT vs. BRAFMut melanoma models or primary patient tumors." (PMID 36539575, 2023). "For instance, although B16F10 cells and melanoma tumors were irradiated with the same dose, LLLT markedly upregulated the expression of VEGF and HIF-1α in B16F10 cells, but not in melanoma tissues." (PMID 36836677, 2023). "In melanoma cells, a regulation of Cyr61 by HIF-1α was suggested, which is not mediated by the direct binding of HIF-1α to the Cyr61 promoter, but via c-Jun/AP-1." (PMID 33540545, 2021). "Cox proportional hazards models for HIF1α (n=46), VEGF (n=45), and bFGF (n=46) expression in the melanoma compartment alone (digital H-score) showed that none was prognostic." (PMID 33552976, 2020).
melanoma (continued). "Although some studies have shown that miRNA-138 negatively regulates HIF1α to affect the proliferation and metastasis of melanoma and ovarian cancer, it is not clear whether the relationship in human melanoma tissues is established and the therapy for targeting miRNA-138 and HIF1α is effective." (PMID 31371307, 2019). "The vast majority of melanoma samples presented high VEGF expression (333 patients, 88.8%), and non-high HIF-1α expression (360 patients, 95.7%)." (PMID 29755400, 2018). "In melanoma, we found that ASS is positively up-regulated by c-Myc and down-regulated by HIF-1α, and epigenetics do not play a major role in ASS regulation." (PMID 28587170, 2017). "DMOG exposure of siRNA-transfected melanoma cells did not result in significant increase of HMGB1 release, therefore reinforcing the role of the hypoxia/HIF1α axis in HMGB1 secretion." (PMID 27426915, 2016). "Using lentiviral transduction of shRNA specific to HIF1α, we demonstrated that decreased PEDF protein levels in melanocytes and melanoma cells were not mediated by HIF1α." (PMID 22457728, 2012). "Surprisingly, chemical simulation of hypoxia using the iron chelator desferrioxamine (DFX), which promotes HIF-1α stabilization, or the prolyl hydroxylase inhibitor dimethyloxalylglycine (DMOG), failed to induce SG formation in either of the melanoma cell lines examined." (PMID 41148289, 2025). "Genetic deletion of HIF-1α, but not HIF-2α, in T lymphocytes leads to accelerated tumor growth and impaired CD8+ T cell tumor infiltration in Lewis lung carcinoma (LLC) and B16F10 melanoma cells." (PMID 35563626, 2022). "However, in high-OXPHOS melanomas, MITF is not suppressed by HIF1α but is promoted by the mammalian target of rapamycin (mTOR), leading to the transcription of PGC1α, a transcriptional coactivator which induces the expression of different OXPHOS genes." (PMID 33498757, 2021). "By studying non-acidic SSM2c and 501-Mel melanoma cells (high- and very low-SOX2 expressing cells, respectively), we confirmed the metabolic role of SOX2, attributing SOX2-driven OxPhos reprogramming to HIF1α pathway disruption." (PMID 30466459, 2018). "In particular, HIF-1α was nearly absent in HEMs, present but at very low levels in the vertical growth phase WM983-A melanoma cell line, and various metastatic melanoma cell lines including WM983-B, which along with the WM-983-A were obtained from the same patient." (PMID 23043612, 2012). "In the isogenic BRAFV600E and BRAFWT melanoma clones cultured under normoxia, differential ROR2 expression was again apparent, but HIF-1α protein was not detectable, suggesting that BRAFV600E acquisition did not promote ROR2 upregulation via HIF-1α stabilization." (PMID 36539575, 2023).
glioblastoma (371 papers, 2007 to 2026). The most malignant astrocytic tumor (WHO grade IV). "In certain contexts, such as glioblastoma, AhR interacts with HIF-1α to control glycolysis, a hallmark of cancer cells." (PMID 41440753, 2025). "HIF1A (hypoxia-inducible factor 1-alpha) has been associated with therapy resistance and poor prognosis in glioblastoma multiforme." (PMID 40338274, 2025). "SP-2 also inhibited angiogenesis by reducing HIF-1α and VEGF in the glioblastoma cells, suggesting that SP-2 has the potential to regulate the HIF-1α-associated pathways and to change cellular and genomic regulation." (PMID 36827114, 2023). "In this sense, it has been described that PINK1 deficiency reprogramed glucose metabolism through HIF1α to maintain cell proliferation and even cancer growth, especially in glioblastoma." (PMID 37047483, 2023). "The trained KPNN models recapitulated characteristic molecular differences between glioblastoma cell states, including an association of HIF1A regulatory importance with MES cells and of ERBB2 with NPC cells." (PMID 32746932, 2020). "A reduced activity of the hypoxia/HIF-1α/STAT5b signaling pathway is associated with epileptogenicity in glioblastomas." (PMID 30621209, 2019). "A previous study found that hypoxia played a crucial role in increasing H19 expression in glioblastoma cells, which was associated with HIF-1α." (PMID 30458806, 2018). "Nrf2 associates with the Bcl-xL and hypoxia-inducible factor-1α (HIF-1α) proteins, which promote cell survival and chemotherapeutic resistance in glioblastomas." (PMID 27187376, 2016). "Detectable HIF1α protein is associated with tumor grade and vascularization of glioblastoma patients whose survival is less than a year." (PMID 24040331, 2013). "In glioblastoma, AhR may interact with HIF-1α to control glycolysis, a hallmark of cancer cell metabolism." (PMID 41440753, 2025). "For instance, loss of TSGA10 expression—common in tumors like glioblastoma —may unleash HIF-1α activity, locking cells into glycolysis, exacerbating ROS production (via mitochondrial uncoupling), and fostering genomic instability." (PMID 40507237, 2025). "Importantly, HIF-1α is also overexpressed in human glioblastoma specimens and is associated with poor patient survival." (PMID 32823915, 2020). "We successfully modeled this niche containing cells of HIF-1α+ quiescent stem-like phenotype by incubating glioblastoma cell spheroids under an appropriately hypoxic condition, and the emergence of HIF-1α+ quiescent stem-like cells was shown to be associated with an enhanced sphere-forming activity." (PMID 26799577, 2016). "Also related to the genes identified in the platinum resistance setting in this work, the downregulation of the transcription factor RUNX1T1, and its associated upregulation of Hypoxia-inducible factor 1α (HIF1α), has been associated with the severity and drug resistance in glioblastoma." (PMID 37686015, 2023). "Similarly, our results demonstrated that KDELC2-mutated glioblastoma cells could secrete angiogenic factors to stimulate endothelial cell hyperplasia via enhanced ROS-mediated HIF-1α expression and cellular autophagy." (PMID 37107298, 2023). "Atypical HIF-1α expression was associated with the Notch1 signaling pathway in both GBM and glioblastoma stem cells (GSC)." (PMID 36183290, 2022). "Thus, the higher HIF-1α expression in central intratumor tissue may be caused by impaired vessels, which is consistent with the perivascular and vascular-invasive niches of glioblastoma." (PMID 35785202, 2022). "Evidence suggests that the mechanism underlying HIF-1α melatonin-dependent regulation might be cell type specific; hence, in U251 and U87 glioblastoma cells, and in HCT116 colon cancer cells, melatonin prevents ROS-dependent PHDs inactivation, promoting HIF-1α proteasomal degradation under hypoxia." (PMID 29207653, 2017).
glioblastoma (continued). "Both STAT3 and HIF-1α play critical regulatory roles in maintaining the M2 immunosuppressive phenotype of TAMs and contribute to immune evasion in glioblastoma." (PMID 41002423, 2025). "Current studies have reported similar findings, indicating that hypoxia-induced reactive oxygen species (ROS) enhance hypoxic adaptation in glioblastoma by driving the HIF-1α-SERPINE1 signaling pathway." (PMID 41584614, 2025). "We further probed the role of HIF-1α in regulating CD47 protein in glioblastoma using a migration assay." (PMID 39781344, 2025). "Treatment of LN229 glioblastoma cells with CoCl2, a chemical hypoxia inducer that stabilizes HIF-1α/HIF-2α under normoxic conditions, resulted in a dose- and time-dependent increase in SAMD9 protein levels." (PMID 41331572, 2025). "Another study revealed that melatonin inhibits tumorigenesis and the invasion of human glioblastoma, possibly by suppressing HIF1-α/VEGF/MMP9 signaling via the regulation of a variety of miRNAs." (PMID 40427575, 2025). "Glioblastoma cells, residing within a hypoxic microenvironment, exhibit high expression of HIF1α and HIF2α." (PMID 40290443, 2025). "In response to hypoxia, all three glioblastoma cell lines showed a robust stabilization of HIF-1α and an increase in BNIP3 protein, with T98G and U87MG also exhibiting an increase in CA-IX protein." (PMID 40123902, 2025). "Curcumin, a bioactive constituent of turmeric, has attracted interest in its capacity to impede HIF-1α stabilization in glioblastoma cells (U87MG)." (PMID 40004215, 2025). "Vorinostat (SAHA), an HDAC inhibitor, reduces HIF-1α expression, thereby inhibiting autophagy in glioblastoma at concentrations of 1–10 μM." (PMID 40004215, 2025). "Hypoxia has been shown to upregulate MMP-2 mRNA expression in U87, U251, U373, and LN18 glioblastoma cell lines through HIF-1α activation, thereby increasing invasive potential." (PMID 41515435, 2025). "Next, we conducted immunoblotting experiments to assess HIF-1α gene expression in glioblastoma in vitro." (PMID 39781344, 2025). "The activation of HIF-1α and HIF-1α (EPAS1) expression has been observed in glioblastoma stem cell-like cells, and HIF triggers ROS formation via the simultaneous activation of NADPH oxidase." (PMID 39940440, 2025). "Collectively, as these findings strongly indicate the overexpression of HIF-1αin glioblastoma, we further investigate the mechanisms through which HIF-1α protein overexpression contributes to its malignancy." (PMID 39781344, 2025). "According to the Ivy Glioblastoma Atlas project, we found that HIF1α, HIF2α, and ABCG2 expression was greater in the microvascular proliferation region (CTmvp) than in the leading-edge region (LE)." (PMID 40370575, 2025). "PX-478, a potent HIF-1α transcription inhibitor, similarly suppresses autophagy in glioblastoma at concentrations ranging from 10 to 50 μM." (PMID 40004215, 2025). "In the glioblastoma microenvironment, hypoxia triggers the increased expression of HIF-1α, which drives TAMs toward an immunosuppressive phenotype and elevates levels of the protease LGMN, thereby enhancing angiogenesis induced by low oxygen conditions." (PMID 40630800, 2025). "LAT1 is a transporter of BCAAs, and studies have found that hypoxia upregulates the mRNA and protein levels of LAT1 and BCAT1 in human glioblastoma (GBM) cell lines through the binding of HIF-1α and HIF-2α to the intron of the BCAT1 gene." (PMID 40438606, 2025). "Honokiol, a chemical extracted from the bark of Magnolia trees, has been shown to diminish HIF-1α expression and stimulate autophagy in glioblastoma, both in vitro and in vivo." (PMID 40004215, 2025). "Glioblastoma exists in a hypoxic environment and highly expresses HIF1α and HIF2α, which bind to GAACGTGCCT to promote high expression of the IGF1R receptor." (PMID 40290443, 2025).